INS (insulin)
Diseases named in the same sentence as INS in open-access papers (continued):
Sharing a sentence is not in itself a finding about the gene and the disease.
Obesity (continued). "Our novel findings demonstrate that the type of dietary protein in HPDs is capable of modulating a variety of obesity-related outcomes, including adipose tissue function, glucose–insulin responses, and pancreatic islet size, independent of overall fat mass and without weight loss." (PMID 41156477, 2025). "Also, insulin serves a pivotal function in enhancing the activation of STAT3 mediated by leptin, which is a transcription factor of considerable importance within a crucial signaling pathway designed to inhibit the development of obesity." (PMID 40283443, 2025). "Just as obesity has been identified as a factor leading to the onset of T2DM, other metabolic impairments might have also prevented the catabolism of amino acids, enhanced insulin secretion, and increased amino acid concentration in the plasma." (PMID 40452790, 2025). "MUO (metabolically unhealthy obesity) individuals are characterized by high liver fat content and visceral fat, while MHO (metabolically healthy obesity) individuals exhibit higher insulin sensitivity, better insulin secretion, and more subcutaneous fat content." (PMID 40412522, 2025). "On the other hand, choline-deficient models induced severe hepatic inflammation, oxidative stress and accelerated fibrosis with great rapidity via the up-regulation of TGF-β1/α-SMA and collagen deposition, without fully recapitulating obesity-driven insulin resistance." (PMID 40221799, 2025). "We present a patient with adolescence-onset diabetes with moderate obesity, negative for multiple autoantibodies and preserved C-peptide levels, who was initially diagnosed T2DM, but subsequent molecular gene testing found INS-MODY due to a novel missense variant (p.His29Tyr)." (PMID 39717432, 2025). "CD248, which has been recently linked with insulin metabolism, NAD(P)H quinone dehydrogenase 1 (NQO1) and tenomodulin (TNMD) were downregulated following LIWL, and expression was reduced in SAT of individuals with or without obesity of the LATC and OA cohorts." (PMID 40229590, 2025). "Obesity-related factors that contribute to this enhanced cardiac fibrosis include increased ROS production, M1 macrophage polarization, increased leptin synthesis leading to activation of MAPK and JAK/STAT signaling pathways, and insulin resistance triggering PI3K/Akt signaling." (PMID 41373812, 2025). "White and red blood cell count, thrombocyte, sodium, glucose, insulin, HbA1c, uric acid, triglyceride, LDL-cholesterol, ASAT/GOT, ALAT/GPT, GGT, alkaline phosphatase, ferritin and CRP values were significantly higher in patients with obesity compared to controls with a normal BMI." (PMID 40463745, 2025). "Thus, obesity is a state in which the negative feedback of insulin in the CNS has become ineffective due to insulin resistance." (PMID 41009753, 2025). "We demonstrated that expression of the miRNA, miR-30a, in WAT positively correlates with insulin sensitivity in mice and people and that adenovirus (Adv) delivery of miR-30a into subcutaneous WAT (i.e., inguinal WAT [iWAT]) enhances insulin sensitivity in mice with diet-induced obesity." (PMID 40471675, 2025). "Additionally, it is the first to determine the correlations of adipocyte geometries with clinical parameters, insulin sensitivity parameters, and adipokines, analyzed separately in participants with or without obesity." (PMID 41271970, 2025). "This supports the notion that IL-6 may impair β-cell function and insulin signaling, contributing to hyperglycemia in the absence of significant obesity." (PMID 41523554, 2025). "Adipose tissue-derived microRNA-450a-5p downregulated DUSP10 and impaired glucose tolerance and insulin sensitivity, and targeted inhibition of microRNA-450a-5p could improve obesity and T2DM, indicating the functional role of microRNA-450a-5p in obesity and T2DM." (PMID 39912972, 2025).
Obesity (continued). "ΔEPORE mice with EPOR restricted to erythroid tissue exhibit decreased energy expenditure and total activity, an age-dependent increase in obesity, and a decrease in glucose tolerance and insulin sensitivity, suggesting that EPO signaling in non-erythroid tissue promotes a lean phenotype." (PMID 39996752, 2025). "Up to 30% of individuals with obesity may exhibit normal insulin sensitivity, a favorable lipid profile, and no signs of hypertension." (PMID 39940942, 2025). "The inflammation hypothesis suggests that obesity is a chronic inflammatory state, and inflammatory factors such as TNF-α, interleukin-1β (IL-1β), and IL-6 can decrease tissue sensitivity to insulin and lead to pathological changes in pancreatic β-cell function." (PMID 40842495, 2025). "In obesity and T2DM, the local accumulation of bioactive metabolites—including diacylglycerols, ceramides, and branched-chain amino acid (BCAA) catabolites—within skeletal muscle, adipose tissue, bone, and fascia contributes directly to tissue-specific insulin resistance and metabolic dysfunction." (PMID 41002965, 2025). "In individuals with T2D and overweight or obesity, an ultra-concentrated RTD pre-meal formulation of a low dose of WP (10 g; 40 kcal) provided as WPM in a 125 mL solution, shortly (15 min) ahead of a lunch meal, reduced PPG, and increased PP insulin and GLP-1 response." (PMID 39852403, 2025). "In addition, the insulin tolerance test (ITT) revealed that unlike mice with obesity that were highly resistant to insulin injection, mice treated with 4-HIL had a significantly lower blood glucose concentration, similar to that in ND mice." (PMID 40917356, 2025). "In stratified analyses, for fasting insulin levels, apparent upward trends could only be observed in a few hierarchies after 2003–2006, i.e., in Hispanic individuals, other racial groups, participants with a PIR < 1.85 and obesity." (PMID 40365140, 2025). "Studies suggested that some people with obesity are not insulin resistant." (PMID 39679900, 2025). "Importantly, insulin therapy is no longer considered the primary driver of obesity in T1DM, as suggested by current evidence." (PMID 40707821, 2025). "Since only male mice were used in these previous studies, we do not know whether female mice lacking NR1D1 would also exhibit similar insulin-sensitive obesity phenotype." (PMID 37961647, 2025). "Other tissues that contribute to EPO activity to improve obesity and glucose homeostasis in obese mice include brown adipose tissue (BAT), in which EPO increased interscapular fat mass, temperature, and secretion of FGF21, a metabolic regulator of glucose homeostasis and insulin sensitivity." (PMID 39996752, 2025). "Obesity-related hormones also demonstrated robust group × time effects: leptin (F = 78.011, p < 0.001, ηp2 = 0.796) and adiponectin (F = 68.594, p < 0.001, ηp2 = 0.774), whereas insulin did not (F = 2.291, p = 0.146, ηp2 = 0.103)." (PMID 41367390, 2025). "Conclusions: d-allulose may improve insulin resistance by reducing TG accumulation in the skeletal muscle, potentially independent of its anti-obesity properties." (PMID 40573161, 2025). "Importantly, local WAT inflammation can induce regional insulin resistance through cytokine release (e.g., IL-1β, TNF, IL-6) without requiring systemic cytokine elevation, underscoring a paracrine component of muscle–adipose crosstalk in obesity." (PMID 41002965, 2025). "However, intervention studies where vitamin D supplementation was used have not been able to report improvements in insulin sensitivity among subjects with prediabetes, overweight and obesity in people of different ethnicities." (PMID 39712337, 2025). "Therefore, we might speculate that children and adolescents with obesity and severe OSA might display hyperinsulinism because of impaired insulin clearance instead of increased insulin secretion." (PMID 40365648, 2025).
Obesity (continued). "Notably, patients with obesity with an endothelial cell-specific deletion of the ADM receptor display improved insulin sensitivity, which was accompanied by enhanced insulin-stimulated endothelial nitric oxide synthase (eNOS) phosphorylation and increased skeletal muscle perfusion." (PMID 41465308, 2025). "While there are some similarities between diet-induced and genetic models of obesity, they differ significantly in insulin sensitivity and hormonal profiles, highlighting that obesity-induced effects are not equivalent to those driven by genetic predisposition." (PMID 40233116, 2025). "Notably, D2Rs in subcutaneous adipose tissue are upregulated in individuals with impaired fasting glucose and T2D, correlating with higher HbA1c and insulin resistance—even independent of obesity—suggesting an early compensatory or pathophysiological role." (PMID 40869170, 2025). "In the control subgroup without obesity, who were expected to be the most metabolically healthy of the four subgroups, we observed the lowest fasting concentrations of total amino acids, glucagon, insulin, and hepatic fat content (as measured by CAP)." (PMID 38276866, 2024). "However, the present results show that at 13 weeks, rats do not show obesity and improve their insulin sensitivity." (PMID 38536791, 2024). "The top biomarkers proposed for study in order of frequency were insulin, glucose, CRP, estrogens, leptin, peptides, and IL-6, with the top conditions in order of frequency: neoplasms, cancer, nutritional and metabolic diseases, overweight, nutrition disorders, obesity, and overnutrition." (PMID 39409896, 2024). "Furthermore, resveratrol improved insulin signal transduction in myotubes from lean individuals but not from individuals with obesity." (PMID 38324260, 2024). "The insulin plasma levels during pregnancy are similar between women with and without obesity." (PMID 39083072, 2024). "Furthermore, this RCT study supports beneficial effects of vitamin D supplementation on metabolic parameters in PCOS women, including significant improvements in BMI, WHR, serum insulin concentrations and HOMA-IR, lipid metabolism parameters, especially in women with obesity or IR." (PMID 39014475, 2024). "Women with obesity, compared to those with normal body weight, showed statistically significant differences in fasting serum levels of creatinine, uric acid, and eGFR, as well as HDL and LDL cholesterol fractions, triglycerides, ALT, GGTP, ALP, CRP, and insulin." (PMID 39769504, 2024). "Insulin-stimulated Akt (Ser473) phosphorylation was higher in lean subjects than subjects with obesity, and insulin-stimulated Akt pSer473 phosphorylation further increased with resveratrol in lean subjects but not in subjects with severe obesity (P < 0.05)." (PMID 38324260, 2024). "It suggests that the level of obesity and liver damage may not yet be sufficient to affect whole-body insulin sensitivity." (PMID 38668337, 2024). "Taken together, it is posited that the relatively short duration of IF and the lack of improvement in insulin sensitivity might account for the unchanged cognitive performance of postmenopausal women with obesity in the present study." (PMID 38443944, 2024). "However, some studies suggest that in males, insulin sensitivity seems to depend more on body fat rather than age, indicating that obesity has a more pronounced impact on IR compared to physiological factors related to age." (PMID 39744239, 2024). "However, in our study, β-cell-specific GHSR deficiency did not alter HFD-induced glucose intolerance or insulin secretion, suggesting differential effects between ghrelin and GHSR under obesity." (PMID 38794702, 2024). "In adipose tissues, KATP channels containing Kir6.2 protein subunits could be related to the increase in free fatty acids and insulin resistance; therefore, pathological processes that promote prolonged adipocyte KATP channel inhibition might lead to obesity due to insulin resistance." (PMID 38612888, 2024).
Obesity (continued). "However, prior work indicated that TCAi were not altered from the basal state following insulin stimulation in myotubes derived from individuals with obesity." (PMID 38561248, 2024). "carriers of the GG genotype may benefit from limiting dietary trans fatty acid intake, as there was no reduction in plasma glucose and insulin despite a hypocaloric dietary intervention in adults with overweight and obesity." (PMID 39519516, 2024). "Nevertheless, the absence of insulin-antagonizing GH action led to undisturbed glucose tolerance, similar to findings in the Ecuadorian cohort of human Laron syndrome patients, who display an increased insulin sensitivity despite obesity." (PMID 38960990, 2024). "Our results are consistent with previous studies that MHO was not protective from cardiometabolic diseases, that obesity could lead to impaired beta-cell function and dysregulated insulin homeostasis compared to normal weight population." (PMID 38548792, 2024). "In addition, the ‘healthy’ metabolic profile seen here mirrors that seen during pregnancy in individuals with obesity who were normoglycaemic compared to those who had GDM and may reflect a comparatively insulin-sensitive state in those who are breastfeeding." (PMID 39048696, 2024). "However, we noticed that the association of HMB with CVD outcomes among young women was independent of obesity, MS, anemia, insulin use, and DM." (PMID 38783294, 2024). "Third, considering that obesity is associated with lower insulin sensitivity and higher risk of GDM, the increased risk of ASD in offspring observed in clinical studies may be mediated by obesity rather than GDM." (PMID 39157677, 2024). "Notably, several studies indicated that fat diet-induced hepatic steatosis perpetuates IR through impaired post-receptor insulin signaling before and independent of the development of obesity." (PMID 38982535, 2024). "Moreover, children and adolescents with obesity display diminished glucagon suppression during an oral glucose tolerance test (OGTT) or an euglycemic–hyperinsulinemic clamp (EHC), dependent on the level of insulin resistance." (PMID 38087928, 2024). "The impaired oxidative capacity of sedentary individuals with obesity could result in the accumulation of metabolites such as diacylglycerols and ceramides, with negative consequences on indices of insulin sensitivity." (PMID 38732623, 2024). "This may be due to the fact that obesity exerts systemic effects on various tissues, leading to increased levels of non-esterified fatty acids (NEFAs), insulin, leptin, and inflammatory factors, as well as decreased adiponectin levels." (PMID 38431748, 2024). "In addition, people with metabolically healthy obesity (MHO) have normal blood lipids, insulin sensitivity, and plasma glucose despite an elevated BMI or WC, and they are less likely to develop cardiovascular disease than individuals with metabolically unhealthy obesity (MUO)." (PMID 39479267, 2024). "Additional reviews summarizing the available evidence on the effects of FMT on obesity and glucose metabolism in humans suggested that FMT derived from lean donors may significantly improve insulin sensitivity in the setting of obesity and metabolic syndrome, but with neutral effects on body weight." (PMID 39200335, 2024). "However, the inevitable result of this paradigm change was increased carbohydrate consumption with induced insulin response, increased energy deposition into adipose tissue, with increased obesity and related chronic non-communicable diseases." (PMID 38212644, 2024). "In congenital or HFFD-induced obesity, there was improvement in glycemic traits and liver function, and a reduction of steatosis, which were not accompanied by reductions in body weight or changes in insulin profile." (PMID 39671241, 2024).
Obesity (continued). "In sum, given the significant sexual dimorphism in obesity comorbidities and the renewed interest in RSG as an anti-diabetic drug, it is worthwhile to investigate whether there is a sexual dimorphism in the insulin-sensitizing effect of RSG on WAT during obesity and inflammation." (PMID 39339665, 2024). "For instance, cyclic mechanical stretch loading of adipose tissue could be explored as a tool to improve insulin sensitivity in patients with obesity and T2D, and the mediatory mechanosensors such as FAK and ROCK may be targeted to further invigorate stretch-induced insulin signaling activation." (PMID 39768098, 2024). "For example, for patients with obesity or high BMI levels, physicians might not prescribe insulin considering its potential weight gain effect." (PMID 39420429, 2024). "While numerous studies showed that lack of OGG1 in mice contributes to obesity and metabolic dysfunction, the precise tissue-specific mechanisms of insulin resistance in Ogg1-KO mice remain unknown." (PMID 39596235, 2024). "There were also significant (p < 0.05) but rather weak correlations between BMI z-score and fasting insulin (r = 0.15), HOMA-IR (r = 0.18), HDL (r = −0.13), HDL (r = −0.18), and uric acid (r = 0.17), to some extent confirming the relationships between the degree of obesity and metabolic disorders." (PMID 39125447, 2024). "In addition, leptin and insulin function synergistically on various POMC neuronal subpopulations to enhance WAT browning and energy expenditure, as well as to protect against diet-induced obesity." (PMID 39590824, 2024). "Aims of the present study were to assess whether there are differences in renal cortex GU rates in a larger sample of people with obesity and healthy nonobese controls under insulin clamp conditions." (PMID 37955868, 2024). "We found this paradox to be explained by GLP-1 delaying gastric emptying and the rate of carbohydrate absorption after a meal, biological actions that dominant direct effects on insulin secretion at the B-cell, both in both normal-weight individuals and in non-diabetic individuals with obesity." (PMID 38890501, 2024). "Moreover, risk of developing T2DM and cardiovascular disease is more elevated in children with obesity, complicated by a significant alteration in insulin sensitivity than peers without IR, given the same BMI." (PMID 38397317, 2024). "However, in multifactorial obesity, exogenous leptin administration does not improve insulin sensitivity, possibly due to leptin resistance." (PMID 38289144, 2024). "Insulin-stimulated IRS1 (Tyr632) phosphorylation increased with resveratrol treatment in lean subjects but not in subjects with severe obesity (1.9 ± 0.2 vs. 1.3 ± 0.1 fold increase over the noninsulin, nonresveratrol-treated condition, for lean vs. severely obese, respectively, P < 0.05)." (PMID 38324260, 2024). "Furthermore, the endocrine and metabolic effects of KD are primarily characterized by a considerable decline in fasting serum insulin, percentage of free testosterone, weight, and luteinizing hormone (LH)/follicle-stimulating hormone (FSH) ratio in females with PCOS and obesity." (PMID 38571924, 2024). "In fact, several animal models of obesity and HFD have also demonstrated that certain HDAC inhibitors can effectively reduce adiposity, improve leptin sensitivity, increase energy expenditure, and improve insulin sensitivity and glucose homeostasis in obese animals." (PMID 39109269, 2024). "Participants with healthy BMI (n=15), overweight BMI (n=29) and obesity (n=161) had samples taken fasting and 30 min post mixed liquid meal for analysis of glucagon-like peptide-1 (GLP-1), PYY, glucose-dependent insulinotropic polypeptide (GIP), insulin and glucagon." (PMID 38490484, 2024). "These individuals presented with obesity, acanthosis nigricans, negative antibodies and normal C-peptide and could potentially be weaned off insulin at follow-up." (PMID 38240751, 2024).